EGFR (epidermal growth factor receptor)
Diseases named in the same sentence as EGFR in open-access papers (continued):
Sharing a sentence is not in itself a finding about the gene and the disease.
cancer (continued). "In our assays, the RTKs EGFR and KDR, both abundantly found as oncogenes in various other cancer types, robustly triggered notochord hyperplasia." (PMID 31221659, 2019). "Cetuximab, a chimeric IgG1 antibody against EGFR, and trastuzumab, a humanized IgG1 antibody against HER-2, are popular therapeutic antibodies that significantly improved the clinical outcome in EGFR- and HER-2-overexpressing human cancers, respectively." (PMID 31610784, 2019). "In total, 91 genes were upregulated while 21 showed lower levels of expression, 12 of them were cancer-related genes: two deleted (CDKN2A and PTPRD) and nine amplified (EGFR among others)." (PMID 31703248, 2019). "In BC, amplification of receptor tyrosine kinases, such as ERBB2, EGFR, IGFR and FGFR1, and/or their upregulation contribute to cancer initiation and progression." (PMID 35582269, 2019). "Among the kinome, the Epidermal Growth Factor Receptor (EGFR) is one of the most studied protein kinases and its relationship with cancer has been known since the 1980’s17." (PMID 30626888, 2019). "In conclusion, among patients with diverse cancers (n = 28,584 from a central laboratory), cfDNA interrogated by clinical-grade NGS revealed that 8.5% of patients with solid cancers harbored EGFR amplification." (PMID 31058253, 2019). "EGFR, IGF1R, LAMA2, MYLK, PIK3CA, PIK3R1, and MYLK are members of the focal adhesion pathway, whose dynamics are highly altered in cancer cells." (PMID 31024613, 2019). "Other researchers proved that quercetin had anti-cancer effects on HeLa cells via the adenosine 5‘-monophosphate -activated protein kinase (AMPK)-induced HSP70 and down-regulation of epidermal growth factor receptor (EGFR)." (PMID 31416279, 2019). "EGFR activation has been proven to promote cancer cell proliferation, EMT and drug resistance, and multiple EGFR pathway genes have been proposed as anti-metastatic drug targets." (PMID 31296175, 2019). "In some cancers, for example NSCLC, it has been described that anti-EGFR therapy induced FGFR signaling." (PMID 31758153, 2019). "Since AXL is considered as an attractive target to overcome the resistance to EGFR-TKIs, several AXL kinase inhibitors, antibody drug conjugates and decoy receptors are currently under investigation in clinical trials for cancer treatment." (PMID 31043587, 2019). "Several studies have suggested that the receptor tyrosine kinase (RTK) family, including EGFR, HER2, HER3, and HER4, is one of the major drug resistance mechanisms against pharmacological therapeutic reagents in different cancers, including NSCLC." (PMID 31795298, 2019). "The targeted anti-cancer agent, lapatinib, is a small molecule inhibitor that directly interferes with EGFR (HER-1)and HER-2 signaling, and indirectly reduces HER-3 signaling, thus suppressing important downstream events." (PMID 30657766, 2019). "They suggested that both EGFR and GLUT1 signalling pathway were also essential for the cancer cells metastases." (PMID 31343107, 2019). "Herein, we present a characterization of the established cell lines and their resistance mechanisms, which comprise the overexpression and hyperactivation of EGFR and MET, the emergence of cancer stem-like cell traits, and elevated invasive abilities." (PMID 31877948, 2019). "In cancer cells, β1 integrin potentiates EGF-mediated EGFR autophosphorylation in vitro and in vivo." (PMID 31109009, 2019). "Coordinated recyclings of MET, EGFR, and other RTKs with Integrins through Rab11-FIP1 have been suggested to play a pivotal role in promoting cancer invasion." (PMID 31595389, 2019). "Upon activation, EGFR activates the RAS-MEK-ERK and PI3K-AKT1 pathways that are central to the growth, survival, and migration of cancer cells." (PMID 30918250, 2019). "In contrast, simultaneous inhibition (inhibitors or knockdown) of EGFR and CXCR7 significantly attenuated cancer cell growth." (PMID 30935067, 2019).
cancer (continued). "EGFR was reported to be the upstream regulator critical for STAT3 phosphorylation in cancer cells and cancer stem- like cells." (PMID 30713819, 2019). "We followed the structure-property-function-disease paradigm proposed by Suresh53 and established connections among EGFR dynamics, cancer metastasis, EMT, cortical actin structures, and EGFR phosphorylation." (PMID 30833579, 2019). "The covalent bond between acrylamide of afatinib and the cysteine residue within the active site of the intracellular tyrosine kinase domain of EGFR, HER2, and HER4 enhances afatinib’s potency against cancer cell growth and induces cancer cell apoptosis." (PMID 31426807, 2019). "AURKB, in combination with EGFR knockdown, have shown enhanced therapeutic effect by inhibiting PC3 cell proliferation and inducing apoptosis in vitro, whereas androgen-dependent cancer cells, LNCaP, remain unaffected by the endogenous expression levels." (PMID 31581661, 2019). "In human cancer, the RTKs RON, MET, and EGFR are frequently co-expressed and promote resistance to targeted therapeutics." (PMID 31867280, 2019). "In AMP cancers, we highlight RAS, NGF and EGFR and axon guidance signaling pathways, since identified miRNAs modulate the expression of target genes with overlapping roles in all three pathways." (PMID 31150430, 2019). "Thus, as previous results have suggested, autophagy may be a double-edge sword capable of either promoting or restraining the survival of EGFRM+ NSCLC cells in hypoxic situations and the EGFR signaling may be a key modulator of the switch between cancer cell survival and death in these conditions." (PMID 31266248, 2019). "Two gain regions contained the well-known oncogenes EGFR (7p11.2) and CCND1 (11q13.3) and several known cancer suppressor genes, such as FHIT (3p14.2–p12.1), FAT1 (4q35.1), CDKN2A (9p21.3), and ATM (11q22.3–q24.3), reside within the 10 deletion regions." (PMID 31159251, 2019). "The unfavorable outcome of patients overexpressing EGFR and HER2 has made EGFR and HER2 as important targets for anti-cancer therapy." (PMID 31569723, 2019). "Noteworthy, although in a different cancer model, UCA1 up-regulation was described to induce acquired resistance to EGFR tyrosine kinase inhibitors (TKIs) in EGFR-mutant NSCLC, and this was correlated to the activation of the AKT/mTOR pathway." (PMID 31275854, 2019). "Aberrant activation of the EGFR and its downstream pro-oncogenic signalling pathways, such as the MAPK and PI3K pathway, promotes cancer cell proliferation, including their chronic initiation and progression through the cell cycle." (PMID 30659329, 2019). "Targeting of growth factor receptors is an obvious anti-cancer strategy and many drugs are designed towards VEGFR (bevacizumab, sunitinib), EGFR (cetuximab, erlotinib), HER2 (trastuzumab, pertuzumab) and PDGFR (imatinib, crenolanib)." (PMID 30559346, 2019). "The anti-cancer drug lapatinib exerts its pharmacological effects by selectively interacting with the ATP-binding cassette of both HER-2 and EGFR, thereby interfering with transmembrane signaling." (PMID 30657766, 2019). "Later, specific inhibition of EGFR expression and activity was reported to notably reduce PTHLH expression in cancer cell lines." (PMID 31293052, 2019). "Despite hampering EGFR and renewing the ADCC reaction, cetuximab can also restrict articulation of VEGF and cancer angiogenesis." (PMID 31717302, 2019). "Both EGFR-NP and RGD-NP were predominantly deposited in locations with dispersion of metastatic cancer cells by targeting the near-perivascular regions and remodeled endothelium of metastasis." (PMID 31356633, 2019). "It targets different proteins such as EGFR, COX-2, STAT3, ERK, JNK, Akt, p38, caspases, Bax etc. which regulate different processes in cancer cells like survival, proliferation, invasion, metastasis, chemoresistance, radiation resistance, and cell death." (PMID 31759370, 2019).
cancer (continued). "EGFR and PTEN regulate the induction and progression of malignant tumors through the PI3K/mTOR signal transduction pathway." (PMID 30863440, 2019). "EGFR signals triggers NF-κB activation through IKK complex and the phosphorylation of IκB which is abnormally constitutively activated in cancer cells and driving tumorigenesis by promoting cell proliferation and metastasis." (PMID 32039029, 2019). "Increased understanding of cancer biology has led to the development of anticancer drugs targeting specific oncogenic substrates such as AKT, BCR-ABL1, EGFR, MET, and the IGF-IR." (PMID 31269742, 2019). "Membrane receptor tyrosine kinases, e.g. EGFR, FGFR, IGF1-R, MET, AXL, KIT, RON, VEGFRs and PDGFRs1, have become important targets for cancer precision therapy." (PMID 29728634, 2018). "With regards to signaling and cancer, ERBB4 activates several of the same downstream proteins as EGFR—such as CBL, STAT5, and SHC but also strongly activates PI3K signaling." (PMID 29342193, 2018). "The epidermal growth factor receptor (EGFR/HER1/ErbB1) is one of the key cancer-driving proteins and an important target of several anti-cancer therapies." (PMID 30127519, 2018). "Studies have demonstrated that JAG1 signaling in cancer cells can activate downstream pathways such as AP-1 (activator protein 1), MAPK (mitogen-activated protein kinases), EGFR (epidermal growth factor receptor), and NF-κB." (PMID 30231940, 2018). "Thereby, EGF and EpEX compete for binding to EGFRex, and EpEX modulates the strength of EGFR signaling to pERK1/2/Slug, repressing EMT in cancer cells." (PMID 30261040, 2018). "This can be particularly applied to proteins such as EGFR and HER2/neu, with the size beyond tens of nanometres, which are used in early cancer screening diagnoses." (PMID 30575738, 2018). "Taken together, the combination of gefitinib and elemene exhibits the remarkably enhanced anti-cancer activity, with potential to overcome EGFR-TKI resistance, to inhibit cancer stemness and to repress cancer development capability in xenograft mice." (PMID 30555330, 2018). "In our current study, we generated an EGFR-CAR using piggyBac transposon-based gene transduction and revealed its therapeutic potential against EGFR-positive human cancers, such as NSCLC." (PMID 29415996, 2018). "EGFR is involved in Jak/STAT, nfb, mTOR and MAPK signaling pathways, thereby influencing cancer cell self-renewal, proliferation, differentiation and migration." (PMID 30587839, 2018). "We verified that EGFR and YAP were simultaneously up-regulated in all the 4 cancer cell lines compared with the normal liver cell HL7702, and only the expression of YAP was positively correlated with EGFR in these cells." (PMID 29449645, 2018). "The PI3K-PKB pathway is a major downstream signaling pathway of epidermal growth factor receptor (EGFR), which is a crucial cell surface receptor involved in cancer cell proliferation." (PMID 30045773, 2018). "On the study of retargeting oHSVs to EGFR and CEA, which is overexpressed in cancer cells, the AAs 2-24 of gD was deleted and a single AA substitution, Y38C, was introduced to ablate the responsiveness to nectin-1." (PMID 30799657, 2018). "Presence of AREG, p-EGFR, p-AKT and p-mTOR was confirmed in the cancer tissue, CRC cells and xenografts by immunohistochemistry (IHC)." (PMID 29419396, 2018). "The combination of Bosutinib with the PI3Kα inhibitor Alpelisib, which has shown good efficacy and tolerability in several cancers, including HNSCC, efficiently inhibited both EGFR/ERK and PI3K pathways in HNSCC cell lines." (PMID 29933569, 2018). "While much information is available about EGFR and HER2 signaling in cancer, less is known about the role of ERBB4." (PMID 29342193, 2018). "Erbb-2 belongs to the family of human epidermal growth factor receptor (HER) and plays a central role in many processes (especially in cancers) such as cell proliferation, survival and metastasis." (PMID 30072783, 2018).
cancer (continued). "EGF and other EGF-like ligands trigger EGFR, which activates downstream pro-oncogenic signaling pathways, including the MAPK cascade (RAS-RAF-MEK-ERK) and PI3K-AKT-mTOR pathway, regulating cancer cell survival, growth and motility." (PMID 29449544, 2018). "The epidermal growth factor receptor (EGFR) plays an important role in the process of carcinogenesis and is of prognostic and therapeutic relevance in several cancer types." (PMID 30093972, 2018). "Early studies revealed the crosstalk between NF-κB and epidermal growth factor receptor (EGFR), describing them as “partners in cancer”." (PMID 30581774, 2018). "In cancer cells, ERK/MAPK is activated by the epidermal growth factor receptor, and Ras, leading to the promotion of proliferation, survival, and metastasis of cancer cells." (PMID 29794990, 2018). "Stability, specificity of binding to EGFR-expressing cells, and processing of [68Ga]Ga-DFO-ZEGFR:2377 by cancer cells after binding were evaluated in vitro." (PMID 30231504, 2018). "Epidermal growth factor receptor (EGFR) is overexpressed in a number of cancers and is the molecular target for several anti-cancer therapeutics." (PMID 29728916, 2018). "More precisely, expression levels of EGFR and HER2 in the basal-like MDA MB 231 cancer cell line, HER2 enriched SKBR3 cancer cell line, luminal A MCF7 cancer cell line and luminal B BT474 cancer cell line were determined by Western blot analysis." (PMID 30388834, 2018). "In order to extend our observations to the human cancer cell setting, we investigated the effect of impairing p110α RBD function in EGFR-mutant human NSCLC cell lines." (PMID 30590030, 2018). "EGFR, ERBB2 and members of the downstream PI3K/Akt and Ras pathways are potential therapeutic cancer targets, and they were all downregulated by the combination treatment." (PMID 30197755, 2018). "The epidermal growth factor receptor (EGFR) is amplified in TNBC and EGFR signalling dynamics impinge on cancer cell survival and disease recurrence." (PMID 29644001, 2018). "Peaks involving important cancer genes such as CCND1, EGFR, ERBB2, FGFR1, AKT1, MYC, KRAS and CDKN2A/2B, which were confirmed in our data." (PMID 30131072, 2018). "Receptor tyrosine kinase signaling (including epidermal growth factor receptor (EGFR) and MET), via the ERK pathway, has been shown to mediate FRA-1 phosphorylation in numerous cancers." (PMID 29382358, 2018). "EGFR belongs to the membrane‐bound ErbB (HER) tyrosine kinase receptor family and is important for maintaining cell survival, differentiation and mitogenesis in various cancer types, including NSCLC." (PMID 29570930, 2018). "Elevated miR-21 is a defining feature of multiple cancers including lung ADC and is observed more frequently in patients with EGFR mutant disease." (PMID 30412601, 2018). "Elevated levels of the EGFR and HER-2 have been identified as common components of multiple cancer types and appear to promote solid tumor growth." (PMID 29455673, 2018). "PRKG1 improves the activity and invasion of cancer cells, and it is also indicated that PRKG1 plays a role as an intermediary in the epidermal growth factor receptor (EGFR)-mediated cell death, likely via apoptotic pathway." (PMID 29301256, 2018). "EHD1, a protein of the C-terminal Eps15 homology domain-containing (EHD) family, plays a role in regulating endocytic recycling, but the mechanistic details involved in EGFR-TKI resistance and cancer stemness remain largely unclear." (PMID 29549343, 2018). "Cell proliferation in cancer was demonstrated to be cross-regulated by KEAP1/NRF2 and EGFR signaling." (PMID 29643973, 2018). "For Erlotinib, we first derived 96 drug sensitivity biomarkers from the CCLE cancer cell line panel and used gene expression data of NSCLC patients’ tumors with mutant EGFR in the calculation of wCOXEN." (PMID 29416679, 2018).
cancer (continued). "MCM7 phosphorylation at Tyr-600 mediated by epidermal growth factor receptor (EGFR)-p56Lyn-axis promotes MCM complex assembly and chromatin loading, consequently enhancing DNA synthesis and cancer cell proliferation." (PMID 30062004, 2018). "MAP4K1 (Mitogen-Activated Protein Kinase Kinase Kinase Kinase 1), which is involved in multiple immune and cancer-related pathways including B cell receptor signaling, JNK, EGF/EGFR, TGF-β, and MAPK signaling, was also regulated by the five TFs." (PMID 30594216, 2018). "PEITC is also known to inhibit EGFR and HER2, which are important growth factors and regulators of Akt in different cancer models." (PMID 29955247, 2018). "Induction of transcription of EGFR by T4—and downregulation of EGFR expression by NDAT—is included below in the ‘Selected Cancer Driver Genes’ section." (PMID 30135398, 2018). "Bovine RNase A binds to EGFR and transmits EGFR downstream signaling, including ERK activation, in various types of cancer cells." (PMID 30534052, 2018). "EGFR inhibitors can suppress cell proliferation signaling mediated by the Ras/Raf/MEK/ERK, and also elevate the oxidative stress and ROS in cancer cells." (PMID 30158525, 2018). "Then we examined uPA, TEM8, EGFR and uPAR expression and the ERK1/2 phosphorylation on frozen cancer tissue sections by immunohistochemistry and immunofluorescence." (PMID 30241478, 2018). "To contrast, anlotinib is a powerful inhibitor of VEGFR/VEGF, Met, and EGFR, which is able to induce apoptosis of CECs and suppress production of VEGF induced by EGFR pathway in cancer cells." (PMID 29856135, 2018). "Phosphorylation of MCM7 mediated by EGFR-p56Lyn and RACK1-Akt promotes MCM complex assembly and chromatin loading, therefore enhancing DNA synthesis and cancer cell proliferation." (PMID 30062004, 2018). "We identified dual inhibitors of both EGFR and PDGFR-β in the nanomolar range which have been initially screened in cancer cell lines to prove a benefit of both EGFR and PDGFR-β inhibition." (PMID 29098884, 2018). "In malignant tumors, it has been described that HER2 and EGFR/HER1 are overexpressed and it has been established that overexpression of EGFR correlates with a worse clinical prognosis." (PMID 30670929, 2018). "We found that the p65 subunit of NF-κB subunit was phosphorylated in mammospheres derived from HER2+ early cancer cells, and lapatinib, a HER2 and EGFR inhibitor, inhibited its phosphorylation." (PMID 29295986, 2018). "The HSP70 and HSP90 chaperones work together to target certain client proteins, including EGFR/HER1 for degradation by the ubiquitin-proteasome system, and inhibitory agents targeting HSPs are one of the potential approaches for cancer therapeutics today." (PMID 30347895, 2018). "In this section, we will describe the well-studied EGFR as a model RTK and its signaling modes, ligands, and therapeutic roles in human cancers." (PMID 30449278, 2018). "However, our study showed that median PFS of EGFR-TKIs was prolonged in second-line than in first-line setting, which may partially be attributable to different influence of first-line treatment on subsequent anti-cancer therapy." (PMID 28702789, 2018). "MiR-217 overexpression prevents interactions of CAGE with EGFR and HER2 in anti-cancer drug-resistant Malme3MR cells." (PMID 30583572, 2018). "Of note, expression of EGF in cancer cells remained unchanged upon exposure to paracrine SPINK1, precluding the possibility of EGFR activation via an autocrine modality by PCa cells." (PMID 30333494, 2018). "Inhibitors of the kinase domain of EGFR and HER-2 have been approved for the treatment of cancer, for example, erlotinib, lapatinib and trastuzumab." (PMID 30477154, 2018). "In this work, the In-check platform was validated to assess the mutational status of KRAS oncogene, the main factor responsible for the development of different cancers, in particular CRC, giving them resistance to anti-EGFR therapies." (PMID 29304017, 2018).